ORMDL1 (ORMDL sphingolipid biosynthesis regulator 1)
Description:
Plays an essential role in the homeostatic regulation of sphingolipid de novo biosynthesis by modulating the activity of the serine palmitoyltransferase (SPT) in response to ceramide levels. When complexed to SPT, the binding of ceramides to its N-terminus stabilizes a conformation that block SPT substrate entry, hence preventing SPT catalytic activity. Through this mechanism, maintains ceramide levels at sufficient concentrations for the production of complex sphingolipids, but which prevents the accumulation of ceramides to levels that trigger apoptosis (By similarity).
Tractability: Antibody: UniProt predicts a signal peptide or a membrane-spanning region. PROTAC: ubiquitination databases record sites on it.
Gene: Protein-coding gene on chromosome 2 (189,766,012 to 189,784,382, reverse strand). Ensembl gene ENSG00000128699.
Subcellular location: Endoplasmic reticulum membrane
Subcellular location (Human Protein Atlas): Endoplasmic reticulum
Pathways (Reactome):
Metabolism: Sphingolipid de novo biosynthesis
Gene Ontology:
Molecular function: protein binding
Biological process: ceramide metabolic process; negative regulation of ceramide biosynthetic process
Cellular component: endoplasmic reticulum; endoplasmic reticulum membrane; serine palmitoyltransferase complex; membrane
Genetic constraint (gnomAD): Loss-of-function variants: 8 observed, 12.53 expected, observed/expected ratio (o/e) 0.64, 90% interval 0.37 to 1.15. The upper end of that interval is the gene's LOEUF score, 1.15, which puts it in group 5 of 6, group 1 being the genes least tolerant of losing a copy. Missense variants: 168 observed, 191.62 expected, observed/expected ratio (o/e) 0.88, 90% interval 0.77 to 1. Synonymous variants: 59 observed, 65.37 expected, observed/expected ratio (o/e) 0.9, 90% interval 0.73 to 1.12.
Homologues: Orthologues: chimpanzee ORMDL1 (100% identical), macaque ORMDL1 (100% identical), guinea pig ORMDL1 (99% identical), pig ORMDL1 (99% identical), dog ORMDL1 (99% identical), mouse Ormdl1 (99% identical), tropical clawed frog ormdl1 (95% identical), zebrafish ormdl1 (93% identical), Drosophila melanogaster ORMDL (48% identical), rat Ormdl1 (44% identical). Paralogues in human: ORMDL3 (84% identical), ORMDL2 (83% identical).
Diseases named in the same sentence as ORMDL1 in open-access papers:
ORMDL1 is named in the same sentence as 12 diseases in open-access papers, as found by Europe PMC text mining. Sharing a sentence is not in itself a finding about the gene and the disease. The quoted sentences say what the papers report.
asthma (2 papers, 2015 to 2020). "The human ORMDL1 and ORMDL2 genes, residing in other chromosomes than the ORMDL3 gene, might also be associated with asthma, as peripheral blood mononuclear cells from asthmatic patients exhibited increased expression of ORMDL1 and ORMDL2 genes." (PMID 33643282, 2020).
acute myeloid leukemia (1 paper, 2020). Acute myeloid leukemia (AML) is a group of neoplasms arising from precursor cells committed to the myeloid cell-line differentiation. "Thus, our study shed light on the specific role of ORMDL1 in different tumors via bioinformatics analysis, particularly in cholangiocarcinoma (CHOL), lymphoid neoplasm diffuse large B cell lymphoma (DLBCL), acute myeloid leukemia (LAML), and thymoma (THYM)." (PMID 33145351, 2020).
breast carcinoma (1 paper, 2018). "We also found that breast cancer patients with low expression levels of ORMDL1 and ORMDL2 had a significantly worse prognosis than those with high expression levels." (PMID 29731990, 2018). "In this study, breast cancer patients with high expression levels of ORMDL1 and ORMDL2 showed significantly better prognosis than those with low expression levels." (PMID 29731990, 2018).
familial Alzheimer disease (1 paper, 2020). A degenerative disease of the brain that causes gradual loss of memory, judgment, and the ability to function socially. "In addition, the expression levels of ORMDL1 were demonstrated to be significantly correlated with familial Alzheimer's disease-related presenilin (PS) mutations, manifesting as elevated ORMDL1 and ORMDL2 levels due to PS deficiency." (PMID 33145351, 2020).
tumor (2 papers, 2020 to 2025). "As a result, the expression levels of ORMDL1 in tumor tissues and normal tissues varied in different cancers, especially significantly upregulated in CHOL, DLBCL, LAML, and THYM." (PMID 33145351, 2020). "Second, high expression of ORMDL1 in cell lines of DLBCL and LAML was verified by the CCLE database, which was consistent with the results in the corresponding tumor samples." (PMID 33145351, 2020). "In our study, we first preliminarily analyzed ORMDL1 expression in tumor tissues and normal tissues using the GEPIA database and found that ORMDL1 was expressed differently in diverse cancer tissues and adjacent tissues, especially highly expressed in CHOL, DLBCL, LAML, and THYM." (PMID 33145351, 2020). "In contrast, expressions of ORMDL1 and ORMDL3 non-significantly differed between tumor and normal brain tissues." (PMID 41049440, 2025).
cancer (1 paper, 2020). A tumor composed of atypical neoplastic, often pleomorphic cells that invade other tissues. "Finally, molecular mechanism investigation should be carried out to further explore cancer pathways associated with ORMDL1 and sphingolipid metabolism." (PMID 33145351, 2020). "The relationship between ORMDL1 and cancer immune cells was investigated, and ORMDL1 expression was positively correlated with infiltrating levels of B cells." (PMID 33145351, 2020). "We emphatically investigated the expression level of ORMDL1 in different types of cancers, the effect of ORMDL1 expression on patient prognosis, and the genetic alterations and the potential interaction of ORMDL1 with related genes especially in DLBCL." (PMID 33145351, 2020). "We further explored the influence of ORMDL1 expression levels on the survival of patients in four cancer types, including CHOL, DLBCL, LAML, and THYM." (PMID 33145351, 2020). "By collecting genetic information from CCLE, investigation of ORMDL1 expression was extended to various cancer cell lines." (PMID 33145351, 2020). "Finally, through LinkedOmics and Pearson correlation test, genes that positively and negatively interacted with ORMDL1 were found and functional analysis in GO and KEGG pathways was further explored, which might be jointly involved in the ORMDL1-related cancer signaling pathways." (PMID 33145351, 2020). "As a result, ORMDL1 mRNA was found to be highly expressed in cell lines of LAML and DLBCL, which ranked 1st and 11th among 40 kinds of cancers." (PMID 33145351, 2020). "In addition, the cBioPortal database was used as a powerful tool for discovering ORMDL1 genetic alterations in DLBCL, since genetic alteration was considered as an important factor in cancer development." (PMID 33145351, 2020). "Secondly, this study only analyzed transcriptional levels of ORMDL1 in cancers, without its posttranslational levels." (PMID 33145351, 2020).
ORMDL1 also shares sentences with these, for which no sentence is quoted: cholangiocarcinoma (1 paper); depression (1); diffuse large B-cell lymphoma (1); iron overload (1); lymphoid neoplasm (1); thymoma (1).